TPO (thyroid peroxidase)
Diseases named in the same sentence as TPO in open-access papers (continued):
Sharing a sentence is not in itself a finding about the gene and the disease.
postpartum thyroiditis (9 papers, 2014 to 2024). A transient autoimmune Inflammatory disorder of thyroid gland that occurs postpartum due to any partum problem. "Anti-TPO antibodies are suspected to cause vasculo-placental complications, such as hypertonia, pre-eclampsia, preterm placenta abruption, postpartum hemorrhage, and postpartum thyroiditis." (PMID 28536577, 2017). "The development of post-partum thyroiditis in our patient, along with positive TPO antibodies, suggests a potential autoimmune basis for her thyroid and seizure-related symptoms." (PMID 38813074, 2024).
psoriasis (9 papers, 2018 to 2025). An autoimmune condition characterized by red, well-delineated plaques with silvery scales that are usually on the extensor surfaces and scalp. "Studies from India and China have found that psoriasis patients often have abnormal thyroid function, with some showing elevated levels of anti-thyroid peroxidase (anti-TPO) antibodies." (PMID 40161193, 2025). "Obese Psoriasis patients with diagnosis onset ≥40 years were significantly more likely to have positive TPO Ab." (PMID 39337081, 2024). "The mean value of anti-TPO Ab was also highly significant (p<0.001**), while anti-TG Ab levels were significantly higher in the psoriasis group than in the control group (p=0.004)." (PMID 38192953, 2023). "The mean values of anti-TPO Ab and anti-TG Ab were significantly higher in psoriasis subjects than in controls (p<0.001 for anti-TPO and 0.004 for anti-TG, respectively)." (PMID 38192953, 2023). "A total of 111 patients with psoriasis were analyzed for thyroid dysfunction, which included thyroid-stimulating hormone, free T3, free T4, and anti-thyroid peroxidase (anti-TPO) antibody levels." (PMID 35415048, 2022). "Risk factors for the development of thyroid dysfunction are TSH within normal range but at the higher limit, small thyroid volume, and positive TPO Abs, especially in psoriasis women." (PMID 33585138, 2021). "Obese patients with psoriasis had positive TPO Ab in 11 (40.7%), and patients with psoriasis with age at onset of (≥40 years) old had positive TPO Ab in eight (42.1%)." (PMID 31157131, 2019). "Significantly higher prevalence of TPO Ab, Tg Ab, hypo-echogenicity, pseudo-nodularity, and increased vascularity was found in patients with psoriasis." (PMID 31157131, 2019). "The prevalence in Psoriasis versus the control was found for TPO Ab (25.0% vs. 9.3%, p = 0.02), Tg Ab (30.4% vs. 11.1%, p = 0.01), hypoechogenicity (30.4% vs. 9.3%, p = 0.02), pseudo-nodularity (16.1% vs. 0%, p = 0.002), and increased vascularity (35.7% vs. 5.6%, p = 0.001)." (PMID 39337081, 2024). "TPO Abs were also found in late-onset psoriasis than early-onset psoriasis." (PMID 33585138, 2021). "The prevalence in psoriasis versus control was for TPO Ab (25.0% vs 9.3%, p = 0.02), Tg Ab (30.4% vs 11.1%, p = 0.01), hypo-echogenicity (30.4% vs 9.3%, p = 0.02), pseudo-nodularity (16.1% vs 0%, p = 0.002), and increased vascularity (35.7% vs 5.6%, p = 0.001)." (PMID 31157131, 2019). "Hence, thyroid evaluation by anti-thyroid antibodies, particularly TPO Ab, and ultrasound should be included in the care of psoriasis patients." (PMID 31157131, 2019). "Additionally, psoriasis has been noted to be associated with increased T3 levels but not with anti-thyroid peroxidase (TPO) or anti-thyroglobulin (TG) antibody positivity and thyroid dysfunction." (PMID 39767917, 2024). "The role of early detection of anti-thyroid antibodies, i.e., anti-TPO Ab and anti-TG Ab, can be of prognostic value in AITD and psoriasis." (PMID 38192953, 2023). "Patients with thyroid dysfunction had a more severe form of psoriasis (both by PASI score and BSA involvement) than those with mild psoriasis (61.9% vs. 38.1%), whereas patients with increased anti-TPO had a milder disease." (PMID 35415048, 2022). "For instance, anti-thyroid peroxidase antibodies (anti-TPO) and anti-thyroglobulin antibodies (anti-TG) are frequently observed in patients with AITDs and reflect a breakdown in immune tolerance, a mechanism also relevant in psoriasis pathogenesis." (PMID 40863211, 2025). "We also found an increase in adipokines-derived cytokines such as leptin in both thyroid disorder and psoriasis; this explains the prevalence of TPO Abs in obese psoriatic patients than non-obese." (PMID 33585138, 2021). "In patients with psoriasis, a higher prevalence of TPO Ab in obese as compared to non-obese, which was significant (four-folds)." (PMID 31157131, 2019).
atherosclerosis (8 papers, 2016 to 2023). A disease characterized by the build-up of fatty material and calcium deposition in the arterial wall resulting in partial or complete occlusion of the arterial lumen. "Other previous studies reported significant association between TPO-Ab and atherosclerosis in euthyroid individuals." (PMID 37658108, 2023). "First, among euthyroid individuals, participants with high–normal TPO-Ab titers have a risk of developing atherosclerosis, as evaluated by CIMT." (PMID 35159980, 2022). "Having a TPO-Ab titer in the normal range was significantly positively associated with baseline atherosclerosis and significantly inversely associated with active arterial wall thickening." (PMID 35159980, 2022). "Having a TPO-Ab titer in the normal range was significantly positively associated with baseline atherosclerosis." (PMID 35159980, 2022). "Since TPO-Ab is associated with atherosclerosis in euthyroid individuals, cardiovascular risk factors might underlie the association between TPO-Ab and TSH values." (PMID 37658108, 2023). "In addition, being in the normal range for TPO-Ab titer was positively associated with atherosclerosis among 1087 euthyroid Japanese individuals; the adjusted OR and 95% CI for atherosclerosis with respect to log-transformed TPO-Ab titer was 2.65 (1.27, 5.51)." (PMID 34627373, 2021). "Therefore, thyroid function could influence the association between TPO-Ab and the progression of atherosclerosis evaluated by CIMT." (PMID 35159980, 2022). "Therefore, low-grade inflammation might be underlying the positive association between having a TPO-Ab titer in the normal range and baseline atherosclerosis in our present study." (PMID 35159980, 2022). "Thus, we hypothesized that having a TPO-Ab titer in the normal range is positively associated with baseline atherosclerosis and inversely associated with active arterial wall thickening among euthyroid individuals." (PMID 35159980, 2022). "It was shown that the incidence of atherosclerosis was even higher in SCH if the anti-TPO antibody was positive." (PMID 35317033, 2022). "After adjusting for known confounding factors, the adjusted odds ratio (OR) and 95% confidence interval (CI) of log (TPO-Ab titer) for baseline atherosclerosis and active arterial wall thickening was 2.16 (1.07, 4.35) and 0.59 (0.37, 0.93), respectively." (PMID 35159980, 2022). "In the Rotterdam study, a greater incidence of atherosclerosis was observed in anti-TPO-positive hypothyroid patients." (PMID 26761929, 2016). "Independent of known confounding factors, having a TPO-Ab titer in the normal range was significantly positively associated with baseline atherosclerosis and inversely associated with active arterial wall thickening." (PMID 35159980, 2022). "Among euthyroid individuals, having an anti-thyroid peroxidase antibody (TPO-Ab) titer in the normal range (negative) is positively associated with atherosclerosis as evaluated based on carotid intima-media thickness (CIMT)." (PMID 35159980, 2022). "In conclusion, among euthyroid individuals, having a TPO-Ab titer within the normal range (negative) is positively associated with baseline atherosclerosis but inversely associated with active arterial wall thickening." (PMID 35159980, 2022). "The main findings of the present study are that having a TPO-Ab titer in the normal range (negative) is positively associated with baseline atherosclerosis but inversely associated with active arterial wall thickening among euthyroid individuals." (PMID 35159980, 2022). "For a sensitivity analysis, we performed a sex-specific analysis for the association between TPO-Ab titers in the normal range (negative) and baseline atherosclerosis and for the association between TPO-Ab titers in the normal range (negative) and active arterial wall thickening." (PMID 35159980, 2022).
follicular adenoma (8 papers, 2008 to 2024). "First, we performed a proof-of-principle study by analyzing the miRNAs in SEVs bearing thyroid peroxidase and revealed the potent ability of this test to discriminate follicular adenoma and follicular cancer of the thyroid gland." (PMID 34572021, 2021). "Interestingly, in benign cold follicular adenomas, a decrease of NIS mRNA levels was reported, whereas the expression of TG, TSHR and TPO was maintained." (PMID 22242190, 2012). "Similar to TPO, CD56 is in low form or lack of expression in PTC, but has a higher expression in normal thyroid tissue, such as follicular adenoma, nodular goiter and papillary hyperplasia." (PMID 30005075, 2018).
lymph node metastasis (8 papers, 2022 to 2026). "Univariate logistic analysis of the risk factors of lymph node metastasis (LNM) in different thyroid peroxidase (TPO) statuses." (PMID 40496557, 2025). "To assess the association of TPO expression with lymph node metastasis and recurrence in patients, we obtained transcriptional expression data and clinicopathological data from TCGA and derived the results by multifactorial analysis." (PMID 37407700, 2023). "Our study showed that reduced TPO expression was significantly associated with lymph node metastasis and recurrence in patients with PTC, and we validated this result in our central cohort." (PMID 37407700, 2023). "Notably, a prior study validated the association between TPO expression levels and lymph node metastasis in patients with PTC." (PMID 39408960, 2024). "To find whether the TPO gene and its encoded protein are associated with lymph node metastasis and recurrence in PTC patients, we conducted a study that included a discovery phase and a validation phase." (PMID 37407700, 2023). "We have investigated that TPO expression may be associated with lymph node metastasis and recurrence in PTC patients through bioinformatics analysis as well as clinical and pathological findings in PTC patients in our center." (PMID 37407700, 2023). "The multivariable modelling showed that tumour tissue localisation (primary tumour or lymph node metastasis), histological subtype, TPO and NIS expression and TERT promoter mutation were each independent predictors of iodine avidity that could explain 68% of the observed variation of iodine avidity." (PMID 37352166, 2023). "logistic regression analysis of lymph node metastasis in PTC showed that age (p = 0.002), pathological T-stage (p < 0.001) and TPO expression (p < 0.001) were significantly associated with recurrence of PTC was significantly associated." (PMID 37407700, 2023). "This is consistent with our results analyzed through the TCGA database, demonstrating the role of TPO expression in predicting lymph node metastasis in patients." (PMID 37407700, 2023). "We have observed in our clinic that TPO expression may have a relationship with lymph node metastasis in PTC patients and their disease recurrence." (PMID 37407700, 2023). "TPO expression was significantly higher in PTC patients without lymph node metastasis than in PTC patients with lymph node metastasis (p < 0.0001)." (PMID 37407700, 2023). "To verify the expression of TPO in PTC tissues and its relationship with lymph node metastasis in patients, we selected a total of 230 tumor samples from PTC patients and their clinical data from the Thyroid Disease Clinic of the First Affiliated Hospital of Kunming Medical University for analysis." (PMID 37407700, 2023). "We then analyzed the relationship between TPO expression and lymph node metastasis in patients by their corresponding clinical data, and the results showed a strong negative correlation between TPO expression and lymph node metastasis in patients (p = 0.004)." (PMID 37407700, 2023). "In our clinical observation, we found that the rate of lymph node metastasis and recurrence in patients with positive TPO expression in PTC tumor tissues may be better than those with negative TPO expression, so TPO may be used as a predictor of lymph node metastasis as well as tumor recurrence." (PMID 37407700, 2023).
pemphigus (8 papers, 2018 to 2025). Pemphigus is a group of rare autoimmune diseases that cause blistering of the skin and mucous membranes (mouth, nose, throat, eyes, and genitals).This conditioncan occur at any age, but often strikes people in middle or older age. "Further investigations are needed to be carried out to identify the pathogenic functions of anti-TPO and anti-Tg antibodies in pemphigus, as well as to identify the potential shared susceptibility genes." (PMID 33796116, 2021). "Here we examined the levels and positivity of anti-TPO and anti-Tg antibodies in 98 Chinese pemphigus patients and 65 healthy controls, and reviewed the available literature on association between increased presence of positive anti-TPO and anti-Tg antibodies and pemphigus, particularly for PV." (PMID 33796116, 2021). "The presence of elevated anti-TPO and anti-Tg antibodies identified in pemphigus patients implied pemphigus and AITDs may potentially share susceptibility genes or alleles." (PMID 33796116, 2021). "Screening for thyroid comorbidities in patients with pemphigus is essential, especially as about 25% of them are anti-TPO seropositive despite an initially normal TSH." (PMID 41552158, 2025). "The presence of higher levels and rates of positivity of anti-TPO and anti-Tg antibodies in pemphigus patients compared to healthy controls was recently confirmed in the Chinese population." (PMID 36211362, 2022). "Our meta-analysis revealed a significant correlation between increased presence of positive anti-TPO and anti-Tg antibodies and pemphigus, particularly for pemphigus vulgaris (PV)." (PMID 33796116, 2021). "Antibody positivity and levels of anti-TPO and anti-Tg antibodies in pemphigus patients as compared to healthy controls were examined." (PMID 33796116, 2021). "Meta−analysis using the fixed−effects model suggested higher prevalence of positive anti-TPO (OR=2.51, 95% CI, 1.56−4.06) and anti-Tg (OR=2.84, 95% CI, 1.30−6.23) antibodies in patients with pemphigus than healthy individuals." (PMID 33796116, 2021). "The prevalence of positive anti-TPO antibody in pemphigus patients varied between 8% and 40%, and that between 2.5% and 12% for anti-Tg antibody." (PMID 33796116, 2021). "Pemphigus patients showed higher levels and antibody positivity of anti-TPO and anti-Tg antibodies than healthy controls." (PMID 33796116, 2021). "Previous studies have demonstrated that patients with pemphigus have elevated levels of autoAbs directed at muscarinic acetylcholine receptors (M3–5) and anti-TPO Abs." (PMID 32555697, 2020). "The mean percentage of pemphigus patient with anti-TPO antibodies among all these studies was 19% (3.6–40%), which is well above the standard incidence of anti-TPO autoantibodies." (PMID 29915578, 2018). "Conversely, two small case-control studies including 15 and 22 patients with pemphigus demonstrated higher detection rate of anti-TPO antibodies in the sera of patients with pemphigus relative to controls." (PMID 29900171, 2018). "Thus, a diagnosis of pemphigus should warrant screening for thyroid function, as well as for anti-TPO antibodies." (PMID 41552158, 2025). "Functions of influencing keratinocyte signalings by anti-TPO antibody may also be a potential explanation for the presence of elevated anti-TPO antibody in pemphigus." (PMID 33796116, 2021). "Likewise, the correlations between pemphigus and anti-TPO/anti-Tg antibody positivity have been reported in several articles." (PMID 33796116, 2021). "In addition, the status of anti-TPO and anti-Tg antibodies were also compared between females and males within PV patients, PF patients or controls, as well as compared for females or males between pemphigus patients and controls." (PMID 33796116, 2021).
pemphigus (continued). "The present study has analyzed the antibody positivity and levels of anti-TPO and anti-Tg antibodies in pemphigus patients as compared to healthy controls, by performing a meta-analysis on 6 published studies, and also by examining our own hospitalized Chinese pemphigus patient population." (PMID 33796116, 2021). "A significant increase was found between pemphigus patients and normal subjects with nAChR (p < .0001) at T1 but not with m3AChR, TPO or VZV Abs." (PMID 32555697, 2020). "Recent studies have suggested that non-DSG autoAbs may contribute to the pathogenesis of pemphigus, including autoAbs directed at acetylcholine receptors (AChR) and thyroid peroxidase (TPO)." (PMID 32555697, 2020). "We hypothesize that levels of IgG autoAbs against TPO and/or AChRs from patients with pemphigus will not be correlated with clinical disease activity or levels of IgG autoAbs against DSG1 or DSG3." (PMID 32555697, 2020). "Based on the accumulating evidence for the potential role of multiple non-Dsg autoantibodies in pemphigus pathogenesis, we further acknowledge that non-Dsg autoantibodies other than anti-TPO and anti-Tg could also be of relevance in cases that are nonadherent to the DCH." (PMID 36211362, 2022). "Using conventional ELISA assays, we set out to determine if our patients with pemphigus had Abs against three of the dominant non-DSG autoantigens, nAChR, M3AChR, and TPO, and if those Ab levels correlated with the levels of anti-DSG Abs, clinical disease activity, and response to therapy." (PMID 32555697, 2020). "This suggests that anti -AChR and -TPO Abs may not play a direct role in the pathogenesis of most patients with pemphigus, but does not rule out a role for non-DSG auto antibodies in distinct subsets of pemphigus patient." (PMID 32555697, 2020).